TADA2A (transcriptional adaptor 2A)
Description:
Component of the ATAC complex, a complex with histone acetyltransferase activity on histones H3 and H4. Required for the function of some acidic activation domains, which activate transcription from a distant site (By similarity). Binds double-stranded DNA. Binds dinucleosomes, probably at the linker region between neighboring nucleosomes. Plays a role in chromatin remodeling. May also promote XRCC6 acetylation thus facilitating cell apoptosis in response to DNA damage.
Synonyms: TADA2L; KL04P; ADA2; hADA2; ADA2A
Gene: Protein-coding gene on chromosome 17 (37,406,884 to 37,479,725, forward strand). Ensembl gene ENSG00000276234.
Subcellular location: Nucleus; Chromosome
Subcellular location (Human Protein Atlas): Nuclear speckles
Genetic constraint (gnomAD): Loss-of-function variants: 30 observed, 61.91 expected, observed/expected ratio (o/e) 0.48, 90% interval 0.36 to 0.66. The upper end of that interval is the gene's LOEUF score, 0.66, which puts it in group 2 of 6, group 1 being the genes least tolerant of losing a copy. Missense variants: 412 observed, 529.36 expected, observed/expected ratio (o/e) 0.78, 90% interval 0.72 to 0.84. Synonymous variants: 179 observed, 178.54 expected, observed/expected ratio (o/e) 1, 90% interval 0.89 to 1.13.
Homologues: Orthologues: chimpanzee TADA2A (100% identical), macaque TADA2A (100% identical), guinea pig TADA2A (99% identical), pig TADA2A (99% identical), rabbit TADA2A (99% identical), dog TADA2A (99% identical), rat Tada2a (98% identical), mouse Tada2a (97% identical), tropical clawed frog tada2a (84% identical), zebrafish tada2a (76% identical), Drosophila melanogaster Ada2a (35% identical). Paralogues in human: TADA2B (28% identical).
Diseases named in the same sentence as TADA2A in open-access papers:
TADA2A is named in the same sentence as 10 diseases in open-access papers, as found by Europe PMC text mining. Sharing a sentence is not in itself a finding about the gene and the disease. The quoted sentences say what the papers report.
neuroblastoma (2 papers, 2022 to 2024). Neuroblastoma (NB) is the most common solid, extracranial childhood tumor. "This study, which was carried out in SH-SY5Y human neuroblastoma cells expressing the BirA∗-fused Myc-tagged WT or mutant (A53T) α-syn, identified transcriptional adapter 2-alpha (TADA2a) as a novel binding partner of α-syn." (PMID 36198386, 2022).
Delusion (1 paper, 2021). A delusion is a fixed false belief held despite evidence to the contrary. "TADA2A is a candidate gene within the schizophrenia-associated 17q12 deletion, and five out of six family members with the splicing variant have schizophrenia-like clinical features (i.e., hallucinations or delusions), including four deletion carriers and one noncarrier child." (PMID 34657631, 2021).
lung carcinoma (1 paper, 2021). "Propofol decreases the level of circRNA transcriptional adaptor 2A (circTADA2A) and exerts anti-tumor effects in lung cancer." (PMID 34775376, 2021).
rectum adenocarcinoma (1 paper, 2023). An adenocarcinoma arising from the rectum. "Through the comparison between tumor and normal samples, TADA2A upregulation was determined in both colon and rectum adenocarcinoma." (PMID 37794386, 2023).
cancer (2 papers, 2021 to 2024). A tumor composed of atypical neoplastic, often pleomorphic cells that invade other tissues. "CircTADA2A, derived from exons 5 and 6 of the transcriptional adaptor 2A (TADA2A) gene, has been implicated in various pathological processes of human cancers." (PMID 38635778, 2024).
TADA2A also shares sentences with these, for which no sentence is quoted: tumor (2 papers); breast carcinoma (1); leukemia (1); lymphoma (1); schizophrenia (1).